RNY3P15 (RNY3 pseudogene 15)
Gene: Miscellaneous RNA gene on chromosome 6 (34,873,831 to 34,873,927, forward strand). Ensembl gene ENSG00000252106.
Homologues: Orthologues: chimpanzee Y_RNA (100% identical). Paralogues in human: Y_RNA (82% identical), RNY3 (81% identical), Y_RNA (81% identical), RNY3P1 (80% identical), Y_RNA (80% identical), Y_RNA (79% identical), RNY3P13 (78% identical), Y_RNA (78% identical), RNY3P14 (77% identical), Y_RNA (77% identical), RNY3P11 (76% identical), RNY3P16 (76% identical), and 90 more.